MSI1 (musashi RNA binding protein 1)
Diseases named in the same sentence as MSI1 in open-access papers (continued):
Sharing a sentence is not in itself a finding about the gene and the disease.
glioblastoma (continued). "Based on what is known regarding the regulation of E2F transcription factors, we decided to test if the previously identified Msi1 direct targets CDK6, CDKN1A/p21, CDKN1B/p27 affect E2F2 and E2F8 levels in glioblastoma cells." (PMID 33804958, 2021). "The most prominent and significant upregulation of MSI1 is observed in low–grade glioma (LGG) and glioblastoma (GBM), and ovarian (OV) and endometrial cancers of the uterine corpus (UCEC)." (PMID 34062997, 2021). "HuR, another important RNA-binding protein is highly expressed in glioblastoma tumors and interacts with 3′UTR of MSI1 which is rich in U and AU sequences." (PMID 32448364, 2020). "The MSI1 protein expression was greater in cancer cells than in hNSCs, except for the KNS42 glioblastoma line." (PMID 22428049, 2012). "In the present study, the decrease in MSI1 in glioblastoma cells led to cell growth retardation and a defect in non-apoptotic cell survival, accompanied by a cell-cycle abnormality, which resulted in an ectopic accumulation of Cyclin B1." (PMID 22428049, 2012). "High expression of MSI1, CHK2, and Rad51 and higher ATM phosphorylation was reported in radioresistant stem-like cells from patient-derived glioblastoma (GBM)." (PMID 34900673, 2021). "Querying the Cancer-Genome-Atlas for MSI1 and TRPM8 mRNA abundances, however, did not confirm such an association in glioblastoma patient specimens (data not shown) suggesting that this phenomenon might be restricted to U251 cells." (PMID 29221175, 2017). "Although the MSI1-binding targets in HEK293 have been described, they are not known in glioblastoma cells, and our future research will be directed at identifying the downstream pathway of MSI1 through microarray analysis and proteomic profiling in glioblastoma cells." (PMID 22428049, 2012). "Importantly, since glioblastoma lines with Msi1 KO displayed increased sensitivity to cell cycle and DNA replication inhibitors, we propose that a drug combination strategy (Msi1 + cell cycle/DNA replication inhibitors) could be a viable treatment option for GBM patients." (PMID 33804958, 2021).
glioma (44 papers, 2008 to 2025). A benign or malignant brain and spinal cord tumor that arises from glial cells (astrocytes, oligodendrocytes, ependymal cells). "MSI1 is strongly associated with stemness properties of cancer cells and de–regulated in a variety of solid cancers including gliomas." (PMID 34062997, 2021). "Since Msi1 has been implicated in regulating cancer stem cells, we also investigated its impact on glioma stem cells (GSCs)." (PMID 33804958, 2021). "In the present study, we investigated whether the oncogene MSI1, which is known as a prognostic factor in several cancers such as breast, ovary, glioma and renal carcinoma encodes any miRNAs." (PMID 37607966, 2023). "Additionally, highly expressed MSI1 are associated with high-grade glioma; as a result, the prognostic potential of MSI1 has been approved by survival analysis." (PMID 27285760, 2016). "Overexpression of Msi1 in the advanced stages of the disease and also the prognosis associated with colon and breast cancers, urothelial, esophageal, cervical cancer as well as central nervous system tumors, including glioma, medulloblastoma, and ependymoma is recorded." (PMID 31231484, 2019). "In H4 glioma cells, shRNA-mediated MSI1 knockdown increased endogenous D2 activity, whereas MSI1 overexpression in HEK293T cells decreased D2 expression." (PMID 38879014, 2024). "MSI1 is considered as an activator in tumorigenesis and its increased expression is reported in many cancers such as lung, pancreas, glioma, breast, and colon cancers." (PMID 37607966, 2023). "A miR-330-3p/MSI1 axis is regulated by LINC01094 to promote glioma cell proliferation, migration, and invasion." (PMID 36824662, 2023). "Musashi-1 (MSI1) and Musashi-2 (MSI1) are RNA binding proteins that negatively regulate PTEN expression in gliomas and colonic epithelium, respectively." (PMID 36830628, 2023). "MSI1 was identified as marker of cancer stem cells (CSCs) arising from different brain cancers including glioma, pediatric brain cancers, medulloblastomas or astrocytomas." (PMID 34062997, 2021). "Msi1 knockdown cells showed ∼50% reduction in glioma sphere formation when compared to control, indicating that Msi1 is a functional regulator of GSCs." (PMID 33763422, 2021). "Linc01094 promotes proliferation, migration and invasion of glioma cells by adsorbing miR-330-3p and upregulating MSI1 expression." (PMID 34819945, 2021). "High level of MSI1 expression has been observed in several tumor tissues 9, 10, 14-17, and is associated with poor survival of grade III/IV gliomas patients." (PMID 31903115, 2020). "In agreement with the proposed role of MSI1 in glioma-initiating stem or progenitor cells, its mRNA expression was also found comparably high in tumor recurrences." (PMID 33291443, 2020). "The RBP Musashi1 (Msi1) has been shown to promote glioma progression when its normal interactions with miR-137 are disrupted." (PMID 33228611, 2020). "The concomitant upregulation of MSI1 and YTHDF1 was associated with decreased survival of glioma patients." (PMID 33317545, 2020). "Collectively, these studies indicated that MSI1 promotes a de-differentiated, stem-like tumor cell phenotype in distinct glioma cell models of pediatric as well as adult origin." (PMID 33291443, 2020). "Our studies, however, suggested that the stabilization of mRNAs by MSI1 substantially contributes to the enhancement of a de-differentiated, stem-like glioma cell phenotype by enhancing the expression of the stem cell markers." (PMID 33291443, 2020). "CRISPR/Cas9-determined essentiality scores support a pivotal role of MSI1 in glioma-derived cells, since in median, these depend on MSI1 significantly more than other cancer cells." (PMID 33291443, 2020). "MSI1 expression was found to be correlated with the proliferative activity and grade of malignancy in glioma, which is the most common form of central nervous system (CNS) tumor that derives from glial cells." (PMID 31824472, 2019).
glioma (continued). "A recent report has indicated that MSI1 is capable of enhancing the growth and/or survival of glioma cells through Notch and PI3K/AKT signaling pathway." (PMID 27285760, 2016). "The underlying mechanism had been implied by the MSI1-mediated inhibition of Numb and the downstream activation of PI3K/AKT pathway in glioma cells." (PMID 27285760, 2016). "Accumulated reports have indicated that MSI1 is able to promote drug resistance and cell survival through various signaling pathways in glioma, but the downstream regulators still remain debating." (PMID 27285760, 2016). "Our results show that MSI1 enhance the growth and/or survival of glioma cells by inducing the Notch and PI3K/Akt signaling pathways, through post-transcriptional regulatory mechanisms." (PMID 22428049, 2012). "Taking these reports and our data together, our current model is that MSI1 plays a role in glioma development by enhancing the self-renewal and survival of glioma cells through the MSI1-Numb-Notch pathway and the MSI1-PTEN-PI3 kinase-Akt pathway." (PMID 22428049, 2012). "Exposure of glioma cells to chemical inhibitors of these pathways reduced the number of spheres and living cells, as did MSI1-KD." (PMID 22428049, 2012). "MSI1-KD treated cells generated a reduced number of glioma spheres and stained positive for M-phase markers." (PMID 22428049, 2012). "Since our results shows MSI1 was involved in glioma survival, we surmised MSI1 was related to the regulation of PTEN-PI3 kinase/Akt pathway." (PMID 22428049, 2012). "Although Msi1 has been reported to be elevated in high grade gliomas and liver cancer, little is known about its function and prognostic value." (PMID 20727204, 2010). "High levels of Msi1 have been reported in tumors such as medulloblastoma, glioma, astrocytoma, retinoblastoma and colorectal adenoma." (PMID 18826648, 2008). "On the other hand, MSI1 expression was higher in more malignant glioma cell lines." (PMID 35052701, 2021). "Knockdown of Msi1 could reduce the activities of the PI3 kinase-AKT signaling pathway through the upregulation of PTEN in glioma cells." (PMID 33758618, 2021). "MSI1 is exceptionally highly expressed in gliomas, including GBM." (PMID 33291443, 2020). "Here, by knocking down MSI1 in glioma cells, we found that MSI1 may promote cell proliferation and survival, and its loss can be detrimental." (PMID 22428049, 2012). "Accordingly, it is possible that PTEN is down-regulated by MSI1 in glioma cells." (PMID 22428049, 2012). "In addition, many studies have shown that MSI1 is up-regulated in tumors such as medulloblastoma, glioma, astrocytoma, retinoblastoma, and colorectal adenoma." (PMID 22428049, 2012). "We hypothesize that competence for cell survival may be regulated by the MSI1-PTEN-PI3 kinase/Akt pathway in glioma cells." (PMID 22428049, 2012). "Therefore, we examined the MSI1-KD mediated alteration of the Numb protein level and Notch activity, as represented by the cleaved-Notch level in glioma cells." (PMID 22428049, 2012). "Indeed, a correlation between high levels of Msi1 expression and poor prognosis has been proposed for glioma and astrocytoma." (PMID 18826648, 2008). "Recently, Msi1 expression has been detected in human gliomas and melanomas, indicating it may be involved in oncogenic development." (PMID 18419830, 2008). "We showed that a significant proportion of MSI1 was cytosolic in samples from patients with high grade glioma but it remains unclear whether MSI1/AGO2 pathway actively participates to tumorigenicity in patients and could also have an impact on tumor recurrence." (PMID 31903115, 2020). "Interestingly, we have recently shown that MSI1 contributes to a resistance against the synergistic effect of valproic acid on temozolomide in a novel combinatorial therapeutic approach for pediatric glioma (NCT03243461)." (PMID 33291443, 2020). "Hence, here we examined the role of MSI1 in the abnormal growth of glioma cells." (PMID 22428049, 2012).
glioma (continued). "Thus, the expression of Msi1 seems to be correlated with the grade of the malignancy and proliferative activity of gliomas, Msi1 may be a useful marker for the diagnosis of central nervous system tumors." (PMID 18419830, 2008). "ZBTB42 is positively related to glioma stem cells marker genes such as CD44, MSI1, Fut4, and NES and the high expression group has a stronger relationship with glioma stemness." (PMID 36762114, 2023). "The increasing importance of MSI1 as a prognostic marker in GBM is also reflected by close correlation between MSI1 expression and overall survival rate from high-grade glioma patients." (PMID 35158774, 2022). "We observed that E2F2 and E2F8 mRNA levels are higher in GBM when compared to normal brain and gliomas grade II and III and, similarly to Msi1, their expression levels decrease during neuronal differentiation." (PMID 33804958, 2021). "To further shed light on the impact of MSI1 on glioma cell differentiation and stem cell characteristics, we focused on the expression of reported GBM-CSC markers, co-expressed with MSI1 in HAL8 tumorspheres." (PMID 33291443, 2020). "According to the TCGA-provided transcriptome data, LGG (low grade glioma) and, most importantly, GBM show the highest expression of MSI1." (PMID 33291443, 2020). "No single marker has been shown to be sufficient to confer stem-cell-like properties, thus a combination of different markers is used to identify and isolate CSC in glioma, including Nestin, Sox2 (SRY-related HMG-box gene 2) and Musashi-1 (Msi-1)." (PMID 25121761, 2014). "In contrast to GAPDH (negative control), selective association with GFP-MSI1 was also determined for the CD44 mRNA, supporting the conserved association of MSI1 and the CD44 mRNA in glioma-derived cell models." (PMID 33291443, 2020). "MSI1 and YTHDF1 demonstrated mildly positive correlation of expression in glioma datasets." (PMID 33317545, 2020). "Intriguingly, we also observed a significant proportion of MSI1 proteins in the cytosol in recurrent glioma samples compared with the non-recurrent samples." (PMID 31903115, 2020). "Furthermore glial tumor markers such as OLIG2 and GLI1 and GSC markers such as MSI1 and SOX2 were also significantly reduced in F3.EGFRviii spheres." (PMID 28830458, 2017). "Strikingly, MSI1 is co-expressed with CD44 in single neoplastic cells at the invasive front of GBMs, supporting the view that MSI1′s role in promoting stem cell properties in gliomas essentially relies on the impairment of miRNA-directed downregulation of stem cell markers like CD44." (PMID 33291443, 2020). "Indeed, GBM, the most malignant form of glioma, exhibited greater MSI1 expression compared with less malignant gliomas and non-neoplastic brain tissue." (PMID 31824472, 2019). "To summarize, MSI1 and YTHDF1 can be considered as negative prognostic markers in gliomas." (PMID 33317545, 2020). "MSI1 and YTHDF1 can be considered as negative prognostic markers in gliomas." (PMID 33317545, 2020).
breast carcinoma (24 papers, 2007 to 2025). "The aim of our study is identification of the molecular cause of maximal expression of MSI1 in epithelial breast cancer cell lines." (PMID 33541259, 2021). "The NPI is correlated with survival in breast cancer patients, underlining that MSI-1 has prognostic significance in breast cancer." (PMID 34291358, 2021). "It is revealed that loss of the two main regulators of asymmetric cell division, MSI1 and Notch1, in these cells causes creation of ERα/PR+ breast cancer." (PMID 32448364, 2020). "Here we show that Msi1 is expressed in approximately two-thirds of primary breast cancers, and is associated with reduced survival." (PMID 20727204, 2010). "Overall, our data demonstrated that MSI1 gene encodes two novel miRNAs in breast cancer cells." (PMID 37607966, 2023). "The present study underlines the potential of MSI-1 as a therapeutic target in breast cancer." (PMID 34291358, 2021). "Furthermore, loss of MSI-1 expression resulted in decreased proliferation and treatment resistance of breast cancer cells and increased apoptosis by competitively binding to tachykinin (TAC1) mRNA with miR-130a and miR-206 to stabilize and increase its translation." (PMID 36059653, 2022). "When the authors subsequently performed MSI-1 knockdown, the metastatic ability of breast cancer cells to the lung was substantially decreased." (PMID 37620963, 2023). "Two precursor structures were predicted within intron 4 of MSI1 and among four potential mature miRNAs, two were confirmed experimentally and also detected in clinical samples of breast cancer." (PMID 37607966, 2023). "Therapy resistance: In vitro, breast cancer cells were more sensitive to irradiation after knockdown of MSI-1 or knockdown of MSI-1 and MSI-2." (PMID 37620963, 2023). "Bi and colleagues demonstrated that MSI-1 expression was strong in breast cancer subpopulations with high metastatic potential and increased cell invasion and circulating tumor cells, potentially by downregulating TIMP3." (PMID 37620963, 2023). "Using methylation analyses in primary breast cancer specimens, Kagara and colleagues found that MSI-1 promotor methylation (which was inversely correlated with gene expression) was lowest in TNBC, similar to other stem cell markers, including CD44 and CD133." (PMID 37620963, 2023). "As a translational repressor of p21 during neural development, Msi-1 also targets p21 in malignances including cervical carcinoma and breast cancer." (PMID 35619161, 2022). "Expression of specific breast cancer stem cells (BCSCs) is seen in aggressive tumors and MSI-1 has been shown to be one of the BCSC-related genes." (PMID 36059653, 2022). "MSI-1, as a prognostic marker in breast cancer, has been identified as a key participant in a variety of malignancies." (PMID 36059653, 2022). "Eventually, according to the results, we concluded that down-regulation of the miR-125b is responsible for uprising of MSI1, which is crucial for maintenance of the epithelial phenotype in breast cancer cells." (PMID 33541259, 2021). "The shape of luminal breast cancer cells transforms to a basal-like appearance when MSI1 is downregulated by RNAi." (PMID 34587981, 2021). "Nanog is another breast cancer stem cell marker that was negatively influenced by the MSI-1 knockdown." (PMID 34291358, 2021). "The results of luciferase reporter assay showed that MSI1 is a direct target for miR-125b in epithelial breast cancer cells." (PMID 33541259, 2021). "It is known to be a direct translational MSI-1 target, including in breast cancer, thus explaining the upregulation seen after MSI-1 knockdown." (PMID 34291358, 2021). "In breast cancer cells, however, an alternative way to activate Notch signaling by MSI1 was proposed to involve preventing the NFYA–26S proteasome axis from inactivating the NOTCH–ICD (intra cellular domain)." (PMID 34062997, 2021).